STAT3 (signal transducer and activator of transcription 3)
Diseases named in the same sentence as STAT3 in open-access papers (continued):
Sharing a sentence is not in itself a finding about the gene and the disease.
tumor (continued). "Studies also have shown that TC-PTP has a tumor suppressive function in breast and colorectal cancers mainly by regulating STAT3 signaling." (PMID 28322331, 2017). "In this study we observed pStat3 expression in tumor PCNSL vessels and cells, moreover we found high levels of total and phosphorylated Stat3 protein in tumor brain compared to normal brain." (PMID 28415725, 2017). "Inhibition of STAT3 phosphorylation in a shift from M2 to M1 polarization has been reported to suppress the growth and metastasis of tumor cells." (PMID 28811825, 2017). "A similar effect is seen in pancreatic cancer, where myeloid-derived IL-6 promotes tumour progression from epithelial precursor lesions through STAT3." (PMID 28210073, 2017). "Correlations of the expression levels with the presence of aberrant vessels were analyzed by confocal laser microscopy analysis, using FVIII as endothelial cell marker, CD133 and nestin as cancer stem cell (CSC) marker, CD20 as tumor cell marker, and Stat3." (PMID 28415725, 2017). "Within the tumor microenvironment, MSCs suppressed the ability of DC-mediated T cell mechanisms including IFNγ secretion and tumor cytotoxicity by reducing the amount of available cysteine excretion through a STAT3 mechanism." (PMID 29181035, 2017). "STAT3 plays a key role in various biological processes, including tumor cell proliferation promotion, survival, tumor invasion, angiogenesis, autophagy, and immunosuppression." (PMID 28085115, 2017). "Stat3 is constitutively activated in various tumor types, contributing to enhanced proliferation, survival, angiogenesis and immune evasion via several mechanisms." (PMID 28069035, 2017). "STAT3 modulates various physiological functions including apoptosis, cell cycle regulation, and tumor angiogenesis through regulation of gene expression, and its constitutive activation is associated with a number of human epithelial cancers." (PMID 29207596, 2017). "The present study showed that PTPRD knockdown significantly increased STAT3 activation in vitro, and promoted tumorigenesis in mice characterized also by high pSTAT3 expression in tumor cells in vivo." (PMID 29228728, 2017). "STAT3 inhibition in numerous cell types within the immune microenvironment has the potential to significantly alleviate tumour immune suppression." (PMID 28276425, 2017). "Since the focus of the model is on tumour cells, the calculated different responses are due to the network-wide regulation over NF-κB and Stat3/5 inside tumour cells." (PMID 29118272, 2017). "The increased levels of p-ERK1/2, p-AKT, and p-STAT3 in the pancreata (especially tumor lesions) of KCH mice were suppressed by treatment with anti-H3 antibody." (PMID 28374746, 2017). "Activation of STAT3 leads to resistance to apoptosis in tumor cells and to a tolerant tumor environment." (PMID 28804688, 2017). "The expression of STAT3 and presence of its active form (i.e., phosphorylated form) is increased in tumor tissues from patients and this pronounced expression indicates a poor prognosis in a variety of cancers." (PMID 29371911, 2017). "Activated ATM leads to activation of transcription factors NF-κB and STAT3, known drivers of tumor growth." (PMID 28337983, 2017). "Prior studies have reported that signal transducer and activator of transcription 3 (STAT3) is an oncogenic transcription factor that can regulate many critical functions including cell proliferation, differentiation and apoptosis in tumor cells." (PMID 28208828, 2017). "Several studies have confirmed that STAT3 inhibition by small molecule inhibitors results in tumor cell apoptosis in both in vitro and in vivo." (PMID 28114390, 2017). "Previous studies indicated that STAT3 plays the principal roles in the anti-tumor function of DMAPT." (PMID 28388532, 2017). "In AN3CA tumour tissue, immunohistochemistry demonstrated that STAT3 is phosphorylated under basal conditions and exogenous IL11 further enhanced this (p < 0.05)." (PMID 28186993, 2017).
tumor (continued). "STAT3 regulates antitumor immunity, affecting innate, and adaptive immunity, cell migration to the tumor site, cytolytic function, and the secretion of cytokines and growth factors from different cells." (PMID 28695716, 2017). "We determined that DT inhibited the protein expression of p-STAT3 and blocked the translocation of STAT3 into the chromatin, as well as suppressed tumor epithelial–mesenchymal transition (EMT) gene expression." (PMID 28157698, 2017). "On the basis of the data we have presented in this report, the selective inhibition of IL-6/STAT3 signalling in the tumour microenvironment provides an attractive target for therapeutic intervention." (PMID 28508871, 2017). "The mutual coactivation of these pathways results in the persistent activation of STAT3 which promotes carcinogenesis by upregulating the expression of IL-6 and additional factors involved in tumor growth and metastasis." (PMID 29333002, 2017). "In CCA cells from representative tumor tissue from a CCA patient, p-STAT3 showed positive expression in the tumor part (left) compared with normal tissue part (right)." (PMID 29029413, 2017). "It was also found that acetylation of STAT3 is elevated in tumors and contributes to tumor progression by inducing DNA methylation." (PMID 29137356, 2017). "Recently, many studies showed that STAT3 pathway is involved in inflammation, proliferation, invasion, and migration of tumor cells." (PMID 28331523, 2017). "Inhibition of the constitutively active Jak/STAT3 in gastric tumor leads to reduced polymorphonuclear inflammation and inhibition of pro-inflammatory cytokines IL-11, IL-6 and IL-1β and reduction of tumor volume in mice." (PMID 28350359, 2017). "The phosphorylation of Signal Transducers and Activators of Transcription 3 (p-STAT3) is closely related to tumor invasion and migration." (PMID 29333928, 2017). "Taking together, the data suggested that QRHX inhibited tumor cell-TAMs interactions possibly through blocking CXCL12/CXCR4/JAK2/STAT3 signaling pathways and then regulated macrophages polarization." (PMID 28630636, 2017). "In certain contexts STAT3 also behaves as a tumour-suppressor protein targeting genes involved in apoptosis and induction of growth arrest." (PMID 27769057, 2016). "These tumor-derived cytokines further induce a pronounced STAT3 phosphorylation in infiltrating immune cells." (PMID 28149296, 2016). "Several of small-molecule STAT3 inhibitors, as well as other classes of agents, have been shown to be effective in targeting STAT3 and inhibiting tumor growth in preclinical models, including HNSCC." (PMID 27027445, 2016). "Taken together, our data have revealed a role for Stat3 in normal and tumor development as well as tumor progression." (PMID 27589562, 2016). "Following treatment with 5-FU, the HCCR and p-STAT3 levels in tumours developed from HCCR-shRNA1-transfected cells were significantly decreased compared with those in the tumours developed from control shRNA-transfected cells (P < 0.05)." (PMID 27052330, 2016). "Numerous evidences indicate that STAT3 plays a central role in the development and progression of many human tumors, and suppression of STAT3 activation leads to growth inhibition and apoptosis in tumor cell lines as well as mouse xenograft models." (PMID 26974964, 2016). "Signal transducer and activator of transcription 3 (STAT3) is, with phospho-STAT3 (pSTAT3) as its activated form, an important oncogenic protein well known for its role in tumor cell proliferation, survival, and invasion." (PMID 27435207, 2016). "The cell lines harbor different known mutational drivers and were xenografted into SCID mice to analyze the influence of STAT3 on their tumor growth behavior." (PMID 27191495, 2016). "In order to analyze the effects of STAT3 signaling on CRC tumor growth in xenografts, we generated stable cell lines with knockdown of STAT3, using lentiviral shRNA constructs." (PMID 27191495, 2016).
tumor (continued). "Brassinin can inhibit the constitutive and inducible STAT3 (Signal transducer and activator of transcription 3) signaling pathway, thereby attenuating tumor growth." (PMID 27898039, 2016). "The relationship between ph-STAT1 and ph-STAT3 tumour cell expression and CSS using Kaplan-Meier log rank test, with relevance to different molecular subtypes, was examined." (PMID 27769057, 2016). "In this study, GH induced Stat3 phosphorylation in GH3 cells, suggesting an autoregulatory positive-feedback loop between Stat3 and GH in somatotroph tumor cells." (PMID 27706259, 2016). "The tie between high glucose and STAT3 activation was confirmed in CCA patients as nuclear p-STAT3 activation was significantly enhanced in tumor tissues of CCA patients with DM." (PMID 26743134, 2016). "In bone metastases, the pattern resembled the primary tumours, with activation of STAT3 prevailing over STAT5." (PMID 27406745, 2016). "STAT3 transcription factors are a point of convergence of several most critical oncogenic signaling and upstream modulators of diverse tumor-promoting factors." (PMID 27833081, 2016). "The relationship between STAT3 activation in tumor cells and components of the innate and adaptive immune responses is complex and multifactorial." (PMID 27148255, 2016). "STAT3 activation of miR-21 and miR-181b-1 has dramatic effects on NF-κB activity in the tumor cells." (PMID 27602766, 2016). "Together, the literature and our current research demonstrate that Stat3 can function as an oncogene or as a tumor repressor depending on the oncogenic driver and developmental context." (PMID 27589562, 2016). "Although the clear link between autophagy activation and induction of STAT3 signaling remains to be elucidated, it has been clearly established that STAT3 is an important mediator in the crosstalk between tumor and immune cells." (PMID 27917371, 2016). "Interleukin 17A (IL-17A), a pro-inflammatory cytokine secreted by CD4+ Th17 cells, triggers tumor cells to produce interleukin 6 (IL-6), which in turn activates STAT3-dependent survival and angiogenesis." (PMID 27341128, 2016). "A large body of evidence has shown that STAT3 is constitutively activated in many mouse tumor models, and more importantly in human cancers including breast, liver, lung, pancreas, prostate, skin, hematological and brain cancers." (PMID 27029037, 2016). "There is evidence showing that inhibition of STAT3 leads to cessation of tumor cell growth and apoptosis." (PMID 27898039, 2016). "Lee H used B16 cells, which have relatively low STAT3 activity and IL-6 expression in cell culture but greatly enhanced STAT3 activity in vivo, achieved at least in part through IL-6 production by the tumor stromal immune cells." (PMID 27129720, 2016). "As an alternative and well-known direct upstream factor for Stat3 activation, we next examined if GA modulates oncogenic Src activity that is involved in tumor progression, metastasis, and angiogenesis." (PMID 27419630, 2016). "Previous reports showed that STAT3 promotes tumor cell survival, proliferation, motility and immune tolerance and is considered as an oncogene." (PMID 27486982, 2016). "In particular, MDSCs isolated from tumor-bearing mice have increased levels of phosphorylated STAT3, as compared to immature myeloid cells from healthy mice, and the expansion of MDSCs is abrogated when STAT3 is inhibited in hematopoietic progenitor cells." (PMID 26700461, 2016). "More important, STAT3 can bind to the promoter region (position-848) of VEGF and regulate the transcription and expression of VEGF directly, which indicated STAT3/VEGF pathway act as an important role in tumor angiogenesis." (PMID 27494878, 2016). "Lastly, we demonstrated that in xenograft NSCLC tumors, physalin A inhibited STAT3 Tyr705 phosphorylation and suppressed the in vivo tumor growth, to a degree comparable to cisplatin but with less detrimental influence to the body weight." (PMID 26843613, 2016).
tumor (continued). "We further showed that the use of a STAT3 inhibitor significantly enhanced the chemotherapeutic efficacy and prolonged the survival of tumor-bearing mice." (PMID 27340780, 2016). "STAT3 is known to be activated by several immunosuppressive cytokines commonly found in the tumor microenvironment, such as IL-10, which, in turn, further promotes the expression of these cytokines through a positive feedback loop." (PMID 27435207, 2016). "SOCS3 is an inducible endogenous negative regulator of STAT3, and it is suggested as a tumor suppressor gene." (PMID 27190500, 2016). "The expression of tumor promoting factors is often regulated by key transcription factors like STAT3 whose aberrant activation ultimately favors accumulation and promotion of neoplastic cells." (PMID 27344176, 2016). "Cyclin D1 and VEGF, all regulated by STAT3, are major players in tumor metastasis and has been shown to mediate tumor invasion." (PMID 26911335, 2016). "Silencing STAT-3 provided a systemic antitumor response downregulating CD4+ Tregs which was reflected in inhibition of tumor growth in various cancer cell lines and metastasis too." (PMID 27413756, 2016). "Recent studies also support the theory that Stat3 acts as an oncogene as well as a tumor suppressor depending on the oncogene-driven context." (PMID 27589562, 2016). "Stable knockdown of STAT3 in xenografts was also monitored in tumor extracts to control for potential escape mechanism during tumor formation." (PMID 27191495, 2016). "STAT3, for example, has been demonstrated to function as a tumour suppressor in GBMs that have lost PTEN expression." (PMID 27083054, 2016). "Recent studies have shown that activation of Akt and STAT3 in tumor cells enhances cell migration and growth." (PMID 27875549, 2016). "Meanwhile, our results suggested not only secretion of IL-11 by TGF-β-stimulated cancer-associated fibroblasts (CAFs) but also EBI3 derived from CRC cells triggers gp130/STAT3 signaling to promote tumor growth." (PMID 27247488, 2016). "Previous reports have shown that patients with low proliferating luminal A tumours have higher ph-STAT3 expression compared to those with the luminal B tumours." (PMID 27769057, 2016). "In the present study, the prognostic role of ph-STAT1 and ph-STAT3 tumour cell expression in different molecular subtypes was examined." (PMID 27769057, 2016). "As reviewed recently, Stat3 can function either as an oncoprotein or a tumor suppressor in the same cell type, depending on the specific genetic background or presence/absence of specific coexisting biochemical defects." (PMID 27626682, 2016). "We have recently shown that tumor-shed sMIC can directly facilitate the expansion of MDSCs through upregulating STAT3 pathways." (PMID 26625316, 2016). "Activation and increased expression of STAT3 contribute to growth promoting, invasive and angiogenic properties of tumor cells in tissue culture and animal models." (PMID 27458446, 2016). "The aberrant STAT3 signaling in tumor cells can suppress the expression of pro-inflammatory danger signals (e.g., IFNγ, TNF, CXCL10), while induces the expression of immunosuppressive factors (e.g., VEGF, IL-10) that inhibit DCs maturation." (PMID 27917371, 2016). "STAT3 takes intrinsic activator effects on cancer inflammation and regulates the tumor microenvironment." (PMID 27274723, 2016). "The activation of STAT3 pathway in tumor cells is mainly due to the effect of tumor released factors and plays a critical role in tumor cell-survival and chemo-resistance." (PMID 26821053, 2016). "It has been previously suggested that the mutual interdependence of STAT1 and STAT3 through heterodimer formation on the chromatin of tumor cells has a crucial influence on cancer cell fate." (PMID 27191495, 2016). "STAT3 activation in DCs results in impaired IL-12 production, leading to defective NK activation and reduced cytolytic activity toward tumor targets as well as tolerogenic, immature DCs." (PMID 27148255, 2016).
tumor (continued). "It is possibile that honokiol also suppressed the STAT3-EMT-promoted CSC-like traits in the microenvironment within the xenograft tumor." (PMID 27012679, 2016). "Mechanistically, GA treatment inhibited Src-Stat3-mediated signaling and decreased the expression of Stat3-regulated tumor promoting genes, subsequently inducing apoptosis and cell cycle arrest in the TKI-resistant lung cancer but not in the TKI-sensitive one." (PMID 27419630, 2016). "STAT3 has been recently recognized as a key therapeutic target to reduce tumor growth and metastasis in different types of cancer." (PMID 26762586, 2016). "UA inhibited the activation of NF-κB and STAT3 and the expression of tumorigenic proteins regulated by these inflammatory transcription factors in tumor tissue." (PMID 26909608, 2016). "In the context of tumor biology, STAT3 is often constitutively activated and phosphorylated in a wide range of epithelial and hematopoietic cancers, largely via paracrine or autocrine stimulation by STAT3-activating cytokines and growth factors." (PMID 27148255, 2016). "STAT3 has been shown to regulate NK lytic activity via transcriptional effects on NK recognition receptors and activating NK ligands on tumor cells." (PMID 27148255, 2016). "STAT1 and STAT3 tumour cell expression appeared to be an important determinant of favourable outcome in patients with invasive ductal breast cancer." (PMID 27769057, 2016). "Using a bioluminescent imaging system, we have shown that inhibiting Stat3 mediated by ES-CM in tumor-bearing mice dramatically decreased both the growth rates and volumes of the tumor." (PMID 27460364, 2016). "STAT3 is a well known transcription factor that plays key roles not only in tumor development and tumor metastasis, but also in immune surveillance and immune response." (PMID 27435207, 2016). "Our study shows that RIPK3 exerts tumor suppressor functions by negatively regulating activation of NF-κB, STAT3 and AKT, thereby protecting from aberrant IEC proliferation and CRC development." (PMID 27344176, 2016). "STAT3 has been classified as an oncogene because activated STAT3 can stimulate oncogenic transformation in cultured cells and tumor formation in nude mice." (PMID 26883202, 2016). "To investigate the effect of JAKi on tumour cell dissemination we employed the 4T1.2 orthotopic model, which shows STAT3 activation, and metastasizes to the lungs and the bone from the primary tumour." (PMID 27406745, 2016). "The authors described that resveratrol downregulates STAT-3 activity and reduces the tumor-evoked regulatory B cells (tBregs) production and activity." (PMID 27834913, 2016). "Direct co-culture of tumor cells and macrophages shows that various factors secreted by activated macrophages, including IL-6, activate STAT3 in tumor cells." (PMID 27793010, 2016). "Taken together, the results of the present study would suggest that both STAT1 and STAT3 act as tumour-suppressor proteins in patients with ductal breast cancer." (PMID 27769057, 2016). "STAT3, known to be important for cancer initiation and tumor progression, was reported to bind directly to the miR-21 promoter upon IL-6 induction." (PMID 27323401, 2016). "Quantitative RT-PCR analysis on the xenograft tumor tissues showed that STAT3-responsive targets were significantly decreased after S3I-201 treatment, whereas GRIM-19 expression was not affected." (PMID 27167343, 2016). "One mechanism by which tumour cell migration is inhibited is likely to be due to direct inhibition of the JAK/Stat3 pathway in CCA cells, which is primarily inhibited by Everolimus, even in conditioned CAF-media." (PMID 27206490, 2016). "An exception is a study testing a specific JAK2 inhibitor in a murine CAC model showing that this compound inhibited de novo neoplasia and led to regression of established tumors, which correlated with STAT3 activation." (PMID 26938566, 2016).